ULK1 (unc-51 like autophagy activating kinase 1)
Diseases named in the same sentence as ULK1 in open-access papers (continued):
Sharing a sentence is not in itself a finding about the gene and the disease.
malaria (1 paper, 2019). Malaria is a serious and sometimes fatal disease caused by a parasite that commonly infects a certain type of mosquito which feeds on humans. "Interestingly, the malaria pigment, hemozoin (HZ),—showed a moderate negative correlation with the mRNA levels of the three genes: ULK1 (rs = -0.57, P < 0.0001), BECN1 (rs = -0.40, P = 0.0088), and MAP1LC3B (rs = -0.42, P = 0.0053)." (PMID 31805150, 2019).
medullary carcinoma (1 paper, 2021). "In spontaneous medullary carcinoma in 7M rats, the expression level of Mapk8 was increased, and the expression levels of two other genes, Ulk1 and Wipi1, were decreased." (PMID 34580369, 2021).
mesothelioma (1 paper, 2020). A usually malignant and aggressive neoplasm of the mesothelium which is often associated with exposure to asbestos. "MRT68921, reported as a ULK1 inhibitor, blocks autophagosome initiation and potentiates chemosensitivity in mesothelioma." (PMID 32873786, 2020).
metastatic colorectal cancer (1 paper, 2022). "Dietary lignans are able to block UNC-51-like autophagy activating kinase 1/2 (ULK1/2), key regulators of metastatic colorectal cancer." (PMID 36555124, 2022).
metastatic prostate carcinoma (1 paper, 2023). A carcinoma that arises from the prostate gland and has spread to other anatomic sites. "Accordingly, a study reported that elevated ULK1, a modulator of autophagy, along with mitochondrion-associated autophagy inhibitor (LRPPRC), could be used as a biochemical marker to assess cancer progression and patient OS in patients with metastatic prostate cancer." (PMID 36983973, 2023).
Nephropathy (1 paper, 2023). A nonspecific term referring to disease or damage of the kidneys. "In contrast, Br-MSCs + EXO, EXOs, and Br-MSCs’ transplantation caused a significant (p < 0.001) downstream regulation of mir-34a, mTOR, and AKT expression, and upstream regulation in SNHG-7, AMPK, and ULK-1 expression, respectively, compared with nephropathy and CM-treated groups." (PMID 37631363, 2023). "There was significant (p < 0.001) upregulation in the mean fold change for the relative expression of mir-34a, mTOR, and AKT and downregulation in the mean fold change for the relative expression of SNHG-7, AMPK, and ULK-1 in the nephropathy and CM-treated rats compared with control ones." (PMID 37631363, 2023).
oculopharyngeal muscular dystrophy (1 paper, 2023). Oculopharyngeal muscular dystrophy (OPMD) is an adult-onset progressive myopathy characterized by progressive eyelid ptosis, dysphagia, dysarthria and proximal limb weakness. "We also show that oculopharyngeal muscular dystrophy (OPMD) mutations engender a switch from autophagosome stimulation to autophagosome inhibition by impairing PABPN1 and HNRNPQ control of the level of ULK1." (PMID 37559347, 2023).
Osteoblastoma (1 paper, 2013). A rare benign bone-forming neoplasm usually arising from the spine. "Here, we discovered that salinomycin induced significant AMPK activation in cultured osteoblastoma cells, which promoted Ulk1 activation and autophagy initiation." (PMID 24358342, 2013).
poliovirus infection (1 paper, 2022). An disease or disorder caused by infection with Enterovirus C. "In fact, we show that pharmacological inhibition of ULK1 further boosts virus assembly and release, and it was previously reported that poliovirus infection partially depletes ULK110." (PMID 36216808, 2022).
Pompe disease (1 paper, 2017). "We, too, observed mTOR‐dependent inhibition of ULK1 in GAA‐KO muscle following TSC knockdown, but in the setting of Pompe disease, this suppression of autophagy turned out to be beneficial as shown by the removal of the autophagic buildup." (PMID 28130275, 2017).
postmenopausal osteoporosis (1 paper, 2023). Metabolic disorder associated with fractures of the femoral neck, vertebrae, and distal forearm. "We hypothesized that KOK and P. lobata extracts could alleviate postmenopausal osteoporosis by stimulating autophagy-activating kinases, such as AMPK and ATG1/ULK1, and regulating mTOR levels." (PMID 37435569, 2023). "We confirmed that the KOK and P. lobata extracts effectively alleviated postmenopausal osteoporosis by regulating autophagy, which was related to the activation of AMPK and ULK1 by ginsenoside and honey in KOK, and regulation of mTOR expression by puerarin in P. lobata." (PMID 37435569, 2023).
prion disease (1 paper, 2015). A transmissible disease that is caused by a protein that is able to induce abnormal folding of normal cellular proteins, leading to characteristic spongiform brain changes, which are associated with neuronal loss without an inflammatory response. "Although we have observed the alterations of ULK1 and p-ULK1 in prion infected cell models, the exact situations of AMPK and AMPK-ULK1 pathway in brain tissues of prion diseases remain unknown." (PMID 26423766, 2015).
renal carcinoma (1 paper, 2022). A carcinoma arising from the epithelium of the renal parenchyma or the renal pelvis. "High expression level of ULK1 has been observed and closely related to poor survival in renal cancer." (PMID 35615533, 2022).
retinal ischemia (1 paper, 2018). A ischemic disease that involves the retina. "Retinal ischemia induced a transient dephosphorylation of mTOR (Ser2448), which corresponded with the kinase deactivation, as confirmed by the decreased phosphorylation of two mTOR downstream targets, ULK1 (Ser757) and 4EBP1 (Thr37/46)." (PMID 30250019, 2018).
sarcopenia (1 paper, 2021). Progressive decline in muscle mass due to aging which results in decreased functional capacity of muscles. "We also assess changes of autophagy signaling and flux in young LM and Ulk1 knockout mice to gain insight into potential mechanisms related to the role of autophagy in the development of sarcopenia." (PMID 33669246, 2021). "The purpose of this study was to investigate the effects of lifelong insufficient Ulk1-mediated autophagy on aging skeletal muscle phenotypes to better understand the contribution of reduced autophagy to sarcopenia." (PMID 33669246, 2021). "We hypothesized that lifelong Ulk1-defiency will exacerbate sarcopenia as indicated by a worsening of skeletal muscle contractile and metabolic function." (PMID 33669246, 2021). "Yet the extent to which Ulk1 influences sarcopenia is unclear." (PMID 33669246, 2021).
scrapie (1 paper, 2015). A fatal disease of the nervous system in sheep and goats, characterized by pruritus, debility, and locomotor incoordination. "In this study, AMPK and ULK1 in the brains of hamsters infected with scrapie strain 263 K and in the scrapie-infected cell line SMB-S15 were analysed." (PMID 26423766, 2015). "IHC assays for ULK1 and its phosphorylated isoforms in brain sections prepared from 263 K-infected and normal hamsters showed strongly positive signals of ULK1 and ULK1-Ser555 in the cerebellum, cortex and brainstem of scrapie-infected animals." (PMID 26423766, 2015). "As one of the important elements in autophagy induction, both ULK1 and ULK1-Ser555 are increased in hamsters infected with scrapie agent-263 K and in SMB-S15 cells." (PMID 26423766, 2015). "In this study, we analysed AMPK and ULK1 in the brains of hamsters infected with scrapie agent-263 K and in the scrapie infected cell line SMB-S15." (PMID 26423766, 2015). "Coincidental with the decrease of mTOR in hamster brains infected with scrapie 263 K, the level of ULK1-Ser757, the downstream substrate of mTOR, increased transiently at the very early stage of infection but then quickly declined and was barely detectable at 70 dpi." (PMID 26423766, 2015). "In the brain tissues of the scrapie-infected hamsters, down-regulation of ULK1-Ser757 during the middle and late stages of infection reflected an activated AMPK-ULK1 pathway." (PMID 26423766, 2015).
Splenomegaly (1 paper, 2016). Abnormal increased size of the spleen. "Interestingly, Ulk1 deficiency has also been reported to result in splenomegaly." (PMID 27193190, 2016).
thalassemia (1 paper, 2023). An inherited blood disorder characterized by a decreased synthesis of one of the polypeptide chains that form hemoglobin. "In our opinion, our results on ULK-1 expression in ErPCs isolated from sirolimus-treated patients are of interest since the role of ULK-1 in the pathophysiology of thalassemias is a topic of active interest and translational applications." (PMID 37894732, 2023).
tongue squamous cell carcinoma (1 paper, 2022). A squamous cell carcinoma that arises from the tongue. "Human oral normal epithelial cells and human tongue squamous cell carcinoma CAL-27 cells were cultured to detect miR-214 and ULK1 levels." (PMID 35692501, 2022).
tuberous sclerosis (1 paper, 2022). Hereditary disease characterized by seizures, intellectual disability, developmental delay, and skin and ocular lesions. "Under energy-sufficiency, AMPK activity is lowered leading to an elevation of mTORC1 via the Tuberous Sclerosis Complex, and autophagy-initiating kinase (Ulk1) activation is prevented by being phosphorylated at Ser 757 by mTORC1." (PMID 36005637, 2022).
viral myocarditis (1 paper, 2025). Myocarditis that is caused by an infection with a viral agent. "In a model of viral myocarditis, trehalose was observed to induce autophagy in B-cells through the AMPK/ULK1 signaling pathway, thereby reducing inflammatory damage." (PMID 40584613, 2025).
tumor (211 papers, 2013 to 2026). "To elucidate the molecular mechanisms underlying tumor regression following Ulk1 depletion, we performed RNA-sequencing analysis of Ulk1 WT and Ulk1 KO KPC cells." (PMID 41408407, 2025). "Conversely, recent studies have implicated a tumor suppressive role of ULK1 and autophagy in various cancer types." (PMID 37607937, 2023). "Compared to WT LN229 cells, ULK1 R170K mutation inhibited tumor growth with decreased cell proliferation and elevated cell death." (PMID 35246531, 2022). "ULK1 mutations reduce autophagy-dependent apoptosis directly and induce tumor proliferation and survival by regulating the mTOR-ULK1 signaling axis." (PMID 34007008, 2021). "ULK1/2 has been linked to diverse oncogenic or tumor-suppressive signalling cascades (e.g., KRASG12D/Copper, PI3K/AKT/mTOR, FAK/RhoA, STK11/liver kinase-B1 [LKB1]) that are engaged in pathogenesis of solid tumors from various types 50-52." (PMID 34345207, 2021). "Assessment of this autophagy-deficient allele in PyMT-driven mammary tumors revealed that the ULK1-complex-functions of FIP200 were indeed essential for tumor development, growth and metastasis." (PMID 32743346, 2020). "Some small molecule drugs targeting ULK1 show inhibitory effects on ULK1 expression and the activity of autophagy, and cause tumor cells to be more sensitive to chemotherapeutic drugs." (PMID 32033142, 2020). "PVT1, as a ceRNA, competes with endogenous miR-20a-5p to increase the expression of ULK1 protein, which is upregulated in a variety of tumor types and associated with tumor progression and chemoresistance." (PMID 32042268, 2020). "Accordingly, NNMT downregulation rescued tumor cells under nutrient deficiency in vivo, which was alleviated by ULK1 inhibitor treatment." (PMID 30093610, 2018). "However, Ulk1 loss oppositely increased a crucial cytokine such as GM-CSF that promotes the tumor-suppressive immune cell populations, through tumor-intrinsic signaling, ultimately leading to a less immune-suppressive TME and further reduced tumor progression." (PMID 41408407, 2025). "High expression of ULK1 is associated with better prognosis and it may inhibit tumor growth by promoting autophagy to remove abnormal proteins and damaged organelles from AML cells." (PMID 39650664, 2024). "Furthermore, in NSCLC cells, autophagy inhibition with rocaglamide (a novel natural molecule capable of targeting ULK1 translation) restored tumor intracellular granzyme B, and thus susceptibility to NK cell killing." (PMID 38071322, 2023). "Notably, expression of ULK1 R170K mutation attenuated low-oxygen-induced phosphorylation of ULK1 T180, Atg13 S355 and Beclin 1 S15, and accordingly further curbed tumor growth with repressed cell proliferation and increased cell death." (PMID 35246531, 2022). "Moreover, the expression level of ULK1 was significantly associated with tumor size and survival time." (PMID 33260729, 2020). "Furthermore, treatment with 2-DG and CQ represses HK2-mediated Warburg effect and ULK1-dependent autophagy activates apoptosis to cause tumor regression." (PMID 29285270, 2017). "These insights expand the autophagy regulatory paradigm and highlight ULK1 glycosylation as a therapeutic target for tumour metabolism modulation." (PMID 41540817, 2026). "Clinical data demonstrate a strong correlation between ULK1 expression levels in tumor tissues and sunitinib response (AUC = 0.9063), suggesting its potential as a predictive biomarker." (PMID 41698049, 2026). "In bladder cancer, O‐GlcNAcylation of the AMPKα subunit inhibits its kinase activity via steric hindrance, inactivating ULK1, suppressing autophagy and promoting tumour survival." (PMID 41540817, 2026). "Beyond its canonical role in autophagy-dependent tumor survival, we found an immune-modulatory function of ULK1 in the PDAC TME." (PMID 41408407, 2025). "ULK1 expression was substantially upregulated in tumor tissues compared with normal tissues (P = 0.0391)." (PMID 40401521, 2025).
tumor (continued). "Functional assays further demonstrated that CM from Ulk1 KO cells impaired the survival of tumor-infiltrating neutrophils including PMN-MDSCs, while enhancing the viability of DCs and CD8+ T cells." (PMID 41408407, 2025). "Tumor-intrinsic deletion of Ulk1 significantly delayed tumor onset, reduced PDAC burden and extended survival." (PMID 41408407, 2025). "Consistently, the expression of ULK1 was significantly increased in TNBC tumor tissues and positively correlated with NSD2 and H3K36me2." (PMID 40097917, 2025). "Lastly, MRT67307 is an ULK1 inhibitor that has demonstrated potential anti-tumor activity by impairing autophagy." (PMID 40362400, 2025). "Collectively, these findings indicate that tumor Ulk1 deletion remodels the pancreatic TME primarily by reducing immunosuppressive immune cell populations, along with a modest increase in cytotoxic lymphocyte infiltration." (PMID 41408407, 2025). "They created mice with a specific deletion of the ULK1 gene in their pancreas and observed the effects on tumor growth." (PMID 41408407, 2025). "The small-molecule inhibitor SBI-0206965 selectively inhibits ULK1 and synergizes with mTOR inhibitors to promote ULK1 degradation and enhance tumor cell apoptosis, outperforming chloroquine (CQ) in efficacy." (PMID 41009794, 2025). "This study provides direct evidence to demonstrate a tumor-promoting function of Ulk1 in a spontaneous PDAC model, suggesting its potential as a promising therapeutic target." (PMID 41408407, 2025). "As research progresses, the value of ULK1 inhibitors in targeting the tumor vasculature and enhancing cancer therapy will become clearer." (PMID 39744218, 2025). "A growing number of evidence suggests that ULK1 exerts autophagy-independent functions that also contribute to tumor progression." (PMID 41408407, 2025). "Their findings showed that removing ULK1 slowed down tumor growth and altered the immune environment around the tumor." (PMID 41408407, 2025). "As given ULK1 is a key factor of autophagy cascade, the inhibitors of ULK1 have showed potential effect in controlling tumor." (PMID 40064873, 2025). "Although ULK1 messenger RNA levels remained unchanged between normal and tumor cells in The Cancer Genome Atlas dataset, multiplex immunohistochemistry revealed elevated ULK1 activity, marked by pATG14, in high-grade human PDAC tissues." (PMID 41408407, 2025). "The resulting accumulation of GAS5 suppresses ULK1(Unc-51-like kinase 1)-mediated autophagy, which is critical for tumour cell survival, effectively halting NSCLC progression." (PMID 40944360, 2025). "Conversely, genetic ablation of ATG7 not only suppresses autophagic flux but also induces MDSC recruitment, thereby counteracting ULK1-mediated immunosuppression alleviation to reinforce an immune-suppressive tumor microenvironment." (PMID 41009794, 2025). "To extend our in vitro findings, we investigated the in vivo role of ULK1 in tumor progression using a syngeneic mouse model." (PMID 41408407, 2025). "Although the importance of autophagy in PDAC has been demonstrated by the tumor-suppressive effects of Atg5 and Atg7 deletion, the role of ULK1, a key initiator of autophagy, remains underexplored in in this context." (PMID 41408407, 2025). "Together, these data demonstrate that Ulk1 depletion suppresses the secretion of key cytokines and chemokines that support the recruitment of tumor-promoting immune cell subsets." (PMID 41408407, 2025). "Our findings suggest that targeting ULK1 is a promising strategy for optimizing aberrant tumor vasculature, as demonstrated in both mouse and zebrafish models." (PMID 39744218, 2025).